IFITM3 (interferon induced transmembrane protein 3)
Diseases named in the same sentence as IFITM3 in open-access papers (continued):
Sharing a sentence is not in itself a finding about the gene and the disease.
influenza (continued). "Wang and colleagues showed that inflammatory immune responses linked to the C/C IFITM3 genotype during H7N9 infection play an important role in the pathogenesis of influenza." (PMID 29121968, 2017). "Ifitm3–/– mice exhibit increased susceptibility to infection with influenza, arthritogenic and encephalitic alphaviruses, respiratory syncytial virus, and West Nile virus." (PMID 28240600, 2017). "Recent studies suggest an association between the Interferon Inducible Transmembrane 3 (IFITM3) rs12252 variant and the course of influenza infection." (PMID 27351739, 2016). "Recent studies suggest a close association between the IFITM3 rs12252 variant (C allele) and influenza severity infection." (PMID 27351739, 2016). "Laboratory diagnosis of influenza infection was performed by RT-PCR, the IFITM3 rs12252 was genotyped by RFLP and tested for association with hospitalization." (PMID 27351739, 2016). "The association between IFITM3 rs12252-C polymorphism and the severity of influenza is currently controversial." (PMID 25314048, 2014). "A recent study demonstrated that the IFITM3 protein significantly restricts the morbidity and mortality associated with influenza, further underscoring the crucial role of IFITM3 in vivo." (PMID 23358889, 2013). "IFITM3 SNP rs34481144, which is located in the IFITM3 promoter region, is associated with lower IFITM3 mRNA levels and has a strong association with disease severity in influenza cohorts." (PMID 36075894, 2022). "Furthermore, hypercytokinemia has been linked to a well-known host influenza susceptibility factor, IFITM3 dysregulation, resulting from the rs12252-C genotype." (PMID 36275684, 2022). "IFITM3 is an innate immunity protein that blocks the fusion of viruses with cell membranes, and deficiencies in IFITM3 are among the only known genetic risk factors in humans for developing severe influenza." (PMID 35544568, 2022). "Therefore, the susceptibility to severe influenza infection should rather be investigated based on haplotypes of the IFITM3 polymorphisms instead of single SNPs." (PMID 34930124, 2021). "The IFITM3 rs-12252 allele has been associated with severe Influenza." (PMID 34434219, 2021). "Another allele of the IFITM3 rs34481144 has been associated with severity of influenza." (PMID 34434219, 2021). "However, the IFITM3 rs12252 allele is only one of several elements in the interferon signaling pathway that has been associated with influenza clinical severity." (PMID 34372607, 2021). "In the Asian population, IFITM3 rs12252 is associated with the severity of influenza infection." (PMID 34659578, 2021). "The authors also investigated and detected in this patient the single-nucleotide polymorphism rs12252-C/C in the gene IFITM3, involved in the encoding of the interferon-induced transmembrane protein 3 and previously linked to increased risk to severe influenza infections." (PMID 33036180, 2020). "In addition, Chen and colleagues found that the IFITM3 rs12252 SNP is associated with an increased risk of severe and mild influenza in Asian and Caucasian populations." (PMID 33138079, 2020). "IFITM3 is a cellular restriction factor that inhibits infection of influenza virus and many other pathogenic viruses, and sequence variants of this gene exhibits ethnic differences This highlights the significant role of IFITM3 genetic variants on the epidemiology of influenza." (PMID 33101356, 2020). "IFITM3 is particularly effective at protecting against influenza virus infection and the absence of this single antiviral protein is associated with exacerbated influenza infection in both mice and humans." (PMID 30650117, 2019). "Moreover, a polymorphism in the human IFITM3 gene (rs12252 T>C) was found in several studies to be associated with severe influenza, although one study reported an association with mild influenza only." (PMID 28257482, 2017).
influenza (continued). "Therefore, we performed this study to identify the association between mild flu and IFITM3 rs12252-C polymorphism, BMI, diabetes and hypercholesterolemia." (PMID 29121968, 2017). "IFITM3 also restricts reovirus cell entry and morbidity and mortality associated with influenza." (PMID 27344170, 2016). "The latest study found that IFITM3 prevented the morbidity and mortality associated with influenza." (PMID 23227098, 2012). "Although no other studies have analyzed IFN-γ profiles in other populations affected by SARS-CoV-2, IFITM3-rs12252-C/C was linked to a high risk of influenza in both the White and East Asian populations, suggesting that this variant may also be largely detected around the globe." (PMID 33036180, 2020). "If future studies conclude that IFITM3 rs12252-C polymorphism is associated with the severity of influenza, further investigations into immune reactions of subjects expressing different IFITM3 isoforms may provide greater insights into the underlying mechanisms." (PMID 25314048, 2014). "Thus, induction of Ifitm3 in AM could serve as a mechanism to promote AM survival and thereby limit the loss of this vital cell type during influenza infection." (PMID 24699679, 2014). "Overall, our findings identify IFITM3 KO mice as an accessible, functionally immunocompetent preclinical model for assessment of influenza vaccines." (PMID 40501891, 2025). "When used in conjunction with the truncated protein NΔ21 of interferon-induced transmembrane protein 3 (IFITM3), the inactivated influenza vaccine can produce high titers of neutralizing antibodies in mice." (PMID 39460306, 2024). "In a study of three independent influenza cohorts, IFITM3 SNP rs34481144-A was enriched in severe patients and prevalent in European populations." (PMID 38275224, 2024). "Interferon-induced transmembrane protein 3 (IFITM3) genetic variation and the severity of influenza infection." (PMID 37456487, 2023). "IHQ analysis confirmed the little IFITM1 and IFITM3 induction in mouse lungs infected with influenza, showing a restricted expression in some bronchial and alveolar epithelial cells, but not infiltrating leukocytes." (PMID 35708622, 2022). "IFITM3 was upregulated in platelets isolated from patients during clinical infections of influenza and dengue virus; due to some modification, there is a lower expression in platelets, and there is an increase in disease severity and mortality in patients." (PMID 35842415, 2022). "Conversely, increased IFITM3 expression was a common feature of severe pandemic influenza A(H1N1) and COVID-19." (PMID 35708622, 2022). "Several polymorphisms which have been known for the susceptibility to influenza infection include CD55, C1QBP, FCGR2A, IFITM3, TNF, RPAIN, LTA and KIR." (PMID 33766078, 2021). "In our previous work, we observed that during HIV-1 and influenza A(H1N1)pdm09 experimental co-infection, HIV-1 particles or HIV-1 surface glycoprotein (gp120), an exogenous CCR5 agonist, reduced influenza replication in an IFITM3-dependent fashion." (PMID 34490131, 2021). "The association between IFITM3 rs12252, and CD55 rs2564978 SNPs and influenza H7N9/H1N1 pdm09 clinical outcomes was examined in Chinese population." (PMID 33766078, 2021). "Specifically, influenza samples maintained higher levels of type I IFN response–associated antiviral ISGs (e.g., IFITM1, IFITM2, IFITM3, OAS2, OAS3, OASL) and antigen presentation genes (e.g., HLA-DRB5, HLA-C, B2M, HLA-B, HLA-E)." (PMID 34618691, 2021). "In a recent review study, the effect of rs12252 in IFITM3 gene on influenza infection was investigated demographically." (PMID 33766078, 2021). "The antiviral restriction factor IFITM3 acts as part of innate immune response initial steps to limit influenza infection." (PMID 32754450, 2020). "A comprehensive knowledge of influenza-IFITM3 interactions is necessary to develop a novel and alternative anti-influenza virus strategy in carriers of the IFITM3 SNP rs12252-C/C." (PMID 32321380, 2020).
influenza (continued). "Even platelets and megakaryocytes were shown to remarkably upregulate IFITM3 to prevent viral progression during influenza infection." (PMID 32595654, 2020). "The mechanism of influenza-IFITM3 interactions affecting the antibody response requires further investigation." (PMID 32321380, 2020). "It is noteworthy to point out that the epithelial cells of the respiratory tract are the initial target of influenza infection, and therefore constitute a good model for assessing the level of expression of IFITM3 during influenza infection." (PMID 32754450, 2020). "IFIT1, IFIT3, IFITM3, MX1, and ISG15 have all been shown to possess anti-influenza activities; however, a genetic variant of IFITM3 has been associated with severe influenza infection and higher hospitalization rate." (PMID 33347425, 2020). "Following influenza infection, cognate antigen induces persistent IFITM3 expression preferentially by lung CD8+ TRM compared to splenic memory CD8+ T cells." (PMID 33815352, 2020). "IFITM3 is known as part of the cellular defense against influenza infection, but also plays a role in cancer progression as its knockdown suppressed migration and invasion in gastric cancer cells." (PMID 31428460, 2019). "In vivo studies showed that Ifitm3–/– confers resistance to influenza infection in both humans and mice 12, 13, 14, 15 but the role of IFITM proteins in adaptive immunity per se has not been explored." (PMID 30365177, 2019). "Cells expressing the EGFP-labeled IFITM3 were consistently much more resistant to influenza infection than control cells." (PMID 30640957, 2019). "More studies are needed to understand the impact of IFITM3 genotype on immune memory in the older population following influenza vaccination." (PMID 29868492, 2018). "For example, lung TRM cells constitutively express the interferon-induced transmembrane protein 3 (IFITM3), which facilitates their survival during secondary challenges with influenza." (PMID 30131803, 2018). "In the present study, indirubin resisted the decrease of IFN-β and IFITM3 protein expressions induced by influenza infection in stressed mice and CORT-loaded A549 cells." (PMID 29285277, 2017). "As interferon inducible transmembrane 3 (IFITM3) is a type 1 interferon inducible transmebern protein, it can restricte many RNA virus entry to the cells including influenza, SARS, ebola, hepatitis C virus." (PMID 28713779, 2017). "Three independently cloned cell lines of the pig and microbat IFITM3 proteins markedly inhibited the infectivity of all influenza HA subtypes tested, including both group 1 and group 2 HAs and highly pathogenic avian H5 and H7." (PMID 25614588, 2015). "siRNA knockdown of endogenous pig and microbat IFITM3 enhanced influenza replication by a similar degree to that seen following knockdown of human IFITM3 or chicken IFITM3." (PMID 25614588, 2015). "As the phenotype of influenza-infected Ifitm3−/− mice is indistinguishable from that of mice deleted for the entire locus (comprising Ifitm1, -2, -3, -5 and -6), Ifitm3 apparently dominates influenza resistance in vivo." (PMID 25614588, 2015). "S-Palmitoylation of IFITM3 on three membrane-proximal cysteine residues enhances membrane affinity and antiviral activity against influenza." (PMID 25614588, 2015). "IFITM1, 2 and 3-like proteins are already known to have anti-viral function in mammals, with IFITM3 specifically shown to restrict the effects of influenza in a mouse knockout model." (PMID 26238195, 2015). "We detect low levels of IFITM3 protein in DCs isolated from the lungs of naïve mice and this expression increased following influenza infection." (PMID 26600246, 2015). "Failure of respiratory DCs to up-regulate IFITM3 following influenza virus infection resulted in impaired trafficking to the draining LN and consequently in impaired priming of an influenza-specific CD8+ T cell response." (PMID 26600246, 2015).
influenza (continued). "IFITM2 and IFITM3 code for interferon-induced transmembrane proteins, which are viral restriction factors that play a role in protecting cells against the entry of influenza and other viruses, as well as other aspects of interferon-signaling." (PMID 25905630, 2015). "To confirm IFITM3 participation in the HIV-1-induced inhibition of influenza replication, we performed IFITM3 knocked down assays." (PMID 24978204, 2014). "It has been demonstrated that IFNs inhibit influenza replication in cell culture and in laboratory animals by the restriction factor IFITM3." (PMID 24978204, 2014). "High MCP-1 levels have been associated with both the profound inflammatory responses observed in Ifitm3-/- mice infected with influenza, and with the increased severity of disease observed in humans with a variant Ifitm3 gene." (PMID 24809749, 2014). "We show here that exposure of A(H1N1)pdm09-infected epithelial cells to HIV-1 viral particles or its gp120 enhanced by 25% the IFITM3 content, resulting in a decrease in influenza replication." (PMID 24978204, 2014). "Here, we found that HIV-1 and gp120 produced a TLR2/4-dependent IFN-like effect towards influenza replication, revealed by the IFITM3-dependent HIV-1- or gp120-induced inhibition of influenza replication." (PMID 24978204, 2014). "IFITM3 expression restricts input viral genome to the endosome by preventing viral fusion, and it was therefore suggested that IFITM3 is necessary and sufficient for blocking the nuclear import of influenza vRNPs." (PMID 24049170, 2013). "As the first indication of the crucial role of IFITM3 only appeared upon infection with influenza and the tissue distribution suggests Ifitm3 is important in multiple organ systems, we challenged the Ifitm3-/- mice with a number of different pathogens." (PMID 24278312, 2013). "We show that Ifitm3 alone makes a significant contribution to the control of influenza in mice and provide further insight into its expression and regulation." (PMID 22969429, 2012). "Collectively, these findings establish a central role for Ifitm3 in limiting acute influenza in vivo, and provide further insight into Ifitm3 expression and regulation." (PMID 22969429, 2012). "We have also observed in unpublished work that IFITM3 KO mice, perhaps the most susceptible mouse model of influenza, do not transmit mouse-adapted influenza virus or mouse-adapted SARS-CoV-2 to non-infected, cohoused KO animals." (PMID 39477971, 2024). "IFITM3 also restricts IL-6 production by targeting Nogo-B in response to influenza and SARS-CoV-2." (PMID 39459876, 2024). "Additionally, a second IFITM3 haplotype on chromosome 11 was previously associated with higher severity of HIV, Dengue, Ebola, and influenza infections." (PMID 36859360, 2023). "There have been few investigations on other IFITM3 SNPs in influenza infection." (PMID 37323564, 2023). "A murine influenza model revealed that IFITM3 dampened the cytokine storm typical of respiratory viruses based on the observation of increased inflammatory and apoptotic responses together with pathologically activated NK cells in the lungs and spleen of IFITM3-deficient mice." (PMID 36466909, 2022). "IFITM3 also restricts IL-6 production in response to influenza and SARS-CoV-2." (PMID 36075894, 2022). "Meanwhile, IFITM3 was expressed similarly between deceased and survivor influenza patients." (PMID 35708622, 2022). "Previously, we observed increased IFITM3 in influenza and COVID-19 patients." (PMID 36194487, 2022). "Interestingly, the NK cell cluster expanded in COVID-19 expressed higher levels of the interferon-stimulated gene IFITM3 than the cluster expanded in CAP-flu." (PMID 34424199, 2021). "Because it was previously shown that rs34481144A and rs12252C could interfere with IFITM3 expression, we analyzed its transcript levels in our genotyped influenza positive clinical specimens." (PMID 32754450, 2020).
influenza (continued). "Additionally, resident lung CD8+ T memory cells present persistent higher levels of IFITM3, which protect these cells to secondary influenza infections." (PMID 32754450, 2020). "IFITM3 plays an important role in the pathogenesis of the influenza disease, and it may serve as a potential target for treatment and management of influenza-associated infection." (PMID 30944006, 2019). "Importantly, intact IFITM3 is essential for defense against severe influenza, indicating the protein exerts potent antiviral activity in the infected host." (PMID 31682595, 2019). "Different studies have described the effect of IFITM3 SNPs in influenza disease severity." (PMID 31574965, 2019). "The analysis of IFITM3 polymorphisms in human influenza patients, although not undisputed, as well as studies with IFITM3 knock-out mice provided evidence that IFITM3 plays an important role in the defense against influenza virus infection." (PMID 31398796, 2019). "The IFITM3 molecule can play a significant role in mice and human influenza infections." (PMID 30135686, 2018). "For example, severe human influenza was reported in association with SNP rs34481144 A/G in the 5′ UTR of a regular IFITM3 gene (not imprinted) that encodes antiviral protein IFITM3 for inhibition of viral entry." (PMID 30687383, 2018). "We have investigated whether any differences in antibody response to various influenza strains is evident when comparing IFITM3 rs12252 genotypes." (PMID 29868492, 2018). "Furthermore, studies of influenza infection have revealed that impaired antiviral immune responses in Ifitm3–/– mice can occur as a consequence of unregulated infection of immune cells." (PMID 28240600, 2017). "Interferon-induced transmembrane protein 3 (IFITM3) is involved in innate responses to flu, dengue fever, and West Nile virus, and it has recently been shown that S-palmitoylation of IFITM3 controls clustering in membrane compartments and its antiviral activity." (PMID 26256475, 2015). "Ifitm3 has a critical role in limiting influenza-induced morbidity and mortality in mice." (PMID 25614588, 2015). "However, anti-influenza restriction by pig IFITM3 was in general lower than that seen for human IFITM3, despite comparable expression levels." (PMID 25614588, 2015). "Of all the IFITMs, IFITM3 is the most potent anti-influenza effector in vitro." (PMID 25614588, 2015). "In humans and mice, IFITM3 limits influenza-induced morbidity and mortality." (PMID 25614588, 2015). "Moreover, high Ifitm3 expression in influenza-specific lung-resident CD8+ memory T cells confers resistance to infection and enhances survival of these cells upon recall infection with the virus." (PMID 24699679, 2014). "The IFITM3 effect on influenza life cycle could toll influenza replication, decreasing viral evolution and, perhaps, contributing to the mild clinical symptoms observed in our groups of HIV-1/A(H1N1)pdm09 co-infected individuals." (PMID 24978204, 2014). "Expression of IFITM3 is essential for efficient control of influenza A virus (FLUAV) and respiratory syncytial virus (RSV) infection in mice and polymorphisms in the IFITM3 locus were found to be associated with the severity of influenza in humans." (PMID 25256397, 2014). "Yount and colleagues recently showed that the mouse IFITM3 protein is not only palmitoylated but also ubiquitinated, and that these posttranslational modifications distinctly regulate the cellular localization of IFITM3 and its anti-influenza activities." (PMID 23358889, 2013). "Mice lacking IFITM3 show increased influenza severity, supporting this association." (PMID 40237465, 2025). "Given the strong effect of perturbations to liquid-ordered membrane components on IAV fusion and prior work showing that host restriction factors such as IFITM3 and Serinc5 alter membrane order and stiffness, we hypothesized that similar effects may control influenza fusion with the plasma membrane." (PMID 40704989, 2025).